INS (insulin)
Diseases named in the same sentence as INS in open-access papers (continued):
Sharing a sentence is not in itself a finding about the gene and the disease.
type 1 diabetes (continued). "Early detection of type 1 diabetes allows insulin treatment to be started sooner, avoids diagnosis as an emergency, gives families time to prepare and the opportunity to benefit from future prevention trials and treatments." (PMID 39623620, 2025). "Childhood type 1 diabetes (T1D) is a chronic disease resulting from autoimmune damage to pancreatic β cells, and it necessitates insulin therapy." (PMID 40310133, 2025). "In type 1 diabetes, systematic reviews of randomized controlled clinical trials demonstrate that metformin reduces total daily insulin dose, often inferring an improvement in insulin resistance." (PMID 41285865, 2025). "Insulin has been of paramount importance for the control of both type 1 diabetes (T1DM) and type 2 diabetes (T2DM)." (PMID 40226177, 2025). "The discovery of insulin transformed type 1 diabetes from an acutely lethal illness to a chronic disease that is managed with insulin dependence." (PMID 41289263, 2025). "Type 1 diabetes is an autoimmune disease characterized by the destruction of pancreatic beta cells and its capacity to secrete insulin." (PMID 41392490, 2025). "Type 1 diabetes mellitus (T1DM) is an autoimmune disease characterized by the destruction of insulin-producing beta (β) cells in the pancreatic islets, leading to insulin deficiency and severe alterations in homeostasis." (PMID 40105562, 2025). "This study was performed in adults with type 1 diabetes to evaluate the effects of dapagliflozin on hormonal determinants of glucose homeostasis and ketogenesis when added to standard insulin treatment." (PMID 40629004, 2025). "Autoimmune destruction of pancreatic β‐cells leads to impaired insulin production and onset of type 1 diabetes (T1D)." (PMID 40019367, 2025). "Type 1 diabetes (T1DM) manifests after a long preclinical phase during which autoimmunity destroys the insulin-producing beta cells of the pancreas." (PMID 40906116, 2025). "Overall, AID systems are superior to other currently available insulin treatments for type 1 diabetes in terms of TIR, but their superiority regarding other glycaemic outcomes has not yet been clearly demonstrated." (PMID 40270713, 2025). "Among adults with type 1 diabetes, bone resorption was suppressed following glucose and insulin challenges with stronger effects observed when glucose was administered orally, likely due to incretin involvement." (PMID 41470880, 2025). "Two other RCTs have recently contrasted SMA with CC during HCL insulin therapy in people with type 1 diabetes, albeit with different HCL systems." (PMID 39560745, 2025). "In children and adolescents living with type 1 diabetes, are automated insulin delivery (AID) systems used in an outpatient setting associated with improvements in measures of glucose management and quality of life compared with standard care?" (PMID 40920375, 2025). "Clinical feasibility for insulin is supported by proof-of-concept human studies in type 1 diabetes where hollow microneedles delivered rapid-acting insulin and lowered postprandial glucose effectively." (PMID 41470488, 2025). "Type 1 diabetes (T1D) is an autoimmune disease in which auto-reactive immune cells selectively target pancreatic β cells, leading to insulin (Ins) insufficiency." (PMID 41223263, 2025). "People with type 1 diabetes who initiated glucose sensor monitoring and received nutrition education on carbohydrate counting and flexible insulin dosing improved their blood sugar compensation more than those without education." (PMID 40121673, 2025). "Leptin levels are low in newly diagnosed patients with type 1 diabetes and increase after the institution of insulin therapy." (PMID 40888596, 2025). "Insulin pump therapy is recommended for youth with type 1 diabetes (T1D) as it enhances quality of life and improves glycemic management." (PMID 40110444, 2025). "In those with MIDD, it is difficult to predict who will develop insulin vs non-insulin dependent diabetes." (PMID 39891580, 2025).
type 1 diabetes (continued). "In this context, we therefore aim to describe the early changes in the short term CGM-related metrics and additional relevant clinical measures in people with type 1 diabetes initiating insulin treatment with Omnipod 5 in a real-world setting." (PMID 41473236, 2025). "Type 1 diabetes is an organ-specific autoimmune disease characterized by the destruction of insulin-producing pancreatic beta cells." (PMID 41000615, 2025). "Type 1 diabetes (T1D) is a complex disease driven by the immune system attacking the insulin-producing beta cells in the pancreas." (PMID 39791749, 2025). "As future work, it is envisioned to integrate a customized, low-cost, and open-source insulin pump to generate a low-cost AIDS that can be used to regulate blood glucose in persons with type 1 diabetes." (PMID 40917291, 2025). "There were seven (20%) participants who had type 1 diabetes and 30 (86%) who received insulin treatment." (PMID 40019498, 2025). "We downloaded continuous glucose monitoring (CGM) data for 60 days from persons with type 1 diabetes using two different systems for automated insulin delivery (AID), A (n = 65) or B (n = 85)." (PMID 40807953, 2025). "For people with type 1 diabetes, there are even more factors likely to impact management due to additional technologies and more complex insulin regimens." (PMID 40324886, 2025). "When stratified by type of diabetes, in pregnant people with type 1 diabetes, those with a ≥30% insulin drop had a significantly lower proportion of nulliparous people compared to controls (14.3% vs. 46.2%, p = 0.044), with no other significant differences." (PMID 41227133, 2025). "Advanced hybrid closed-loop (AHCL) systems represent the state of art of insulin therapy in people with type 1 diabetes (T1D)." (PMID 39576311, 2025). "Due to their unique mechanism of action, SGLT2 inhibitors can be combined with other glucose-lowering agents, including insulin, and often reduce the required insulin dosage in both Type 2 and Type 1 diabetes." (PMID 40430150, 2025). "Some cases of fulminant type 1 diabetes improve insulin secretory capacity, like this case and the previous similar cases." (PMID 40406776, 2025). "Human studies have shown PD-L1 expression in residual insulin-positive islets and linked checkpoint pathway disruption to ICI-associated insulin-dependent diabetes in patients receiving anti-PD-1/PD-L1 therapy." (PMID 41463504, 2025). "In newly diagnosed children and young adults with overt type 1 diabetes, golimumab improved endogenous insulin production and reduced the need for exogenous insulin compared with placebo." (PMID 40142915, 2025). "This also applies to type 1 diabetes with long-acting insulin degludec and continuous insulin pumps that utilize rapid-acting insulin." (PMID 40560030, 2025). "High doses of STZ severely impair insulin secretion, similar to the characteristics of type 1 diabetes." (PMID 40362229, 2025). "Fatty acid profile of the plasma phospholipid fraction of Wistar rats induced to develop type 1 diabetes by alloxan and the influence of insulin and Arasco oil (rich source of AA) on the same." (PMID 40005295, 2025). "Treatment with S. macrophylla and glibenclamide led to elevated insulin levels in STZ-induced Type 1 diabetic rats, improving glucokinase activity and thereby enhancing glucose utilisation." (PMID 41244237, 2025). "Type 1 diabetes mellitus is a systemic autoimmune disease characterized by the destruction of pancreatic β-cells, resulting in inadequate insulin production and impairing glucose, lipid, protein, and mineral metabolism." (PMID 41149631, 2025). "Adequate insulin dosing in type 1 diabetes poses significant challenges: achieving near-normal glycaemic management needs to be balanced with minimising the risk of acute hypoglycaemia and long-term complications." (PMID 40629004, 2025).
type 1 diabetes (continued). "Type 1 diabetes is a lifelong condition that begins when the body’s immune system mistakenly destroys insulin-producing beta cells in the pancreas." (PMID 40906116, 2025). "Type 1 diabetes necessitates lifelong basal and prandial insulin therapy to maintain glycemic control, typically requiring multiple daily injections—a factor that significantly impacts quality of life." (PMID 40937414, 2025). "The first identified SNX19 interactor is islet antigen 2, a major autoantigen in type 1 diabetes, which is involved in the regulation of insulin secretion by pancreatic β cells and dopamine release in PC12 cells." (PMID 40002894, 2025). "The fact that plasma total sialic acid levels in patients with type 1 diabetes are relatively unchanged is probably due to the use of insulin for treatment." (PMID 41301440, 2025). "A person with type 1 diabetes (T1D) is dependent on insulin therapy, and needs to make frequent dosing decisions to achieve glycemic targets." (PMID 40777803, 2025). "When someone has type 1 diabetes, their immune system mistakenly targets and destroys β-cells in the pancreas, which produce insulin, the hormone that helps bring down sugar levels in the blood after we eat." (PMID 40232951, 2025). "Type 1 diabetes (T1D) is characterized by the autoimmune destruction of the insulin-producing beta cells, and there is no cure yet for the disease." (PMID 39989961, 2025). "Managing type 1 diabetes (T1D) involves keeping track of a lot of health information, like blood sugar levels, insulin doses, and food intake." (PMID 41171736, 2025). "These systems have been primarily applied to patients with type 1 diabetes but are now expanding to all insulin-dependent patients." (PMID 40415035, 2025). "Background and Objectives: Automated insulin delivery (AID) systems represent a major advancement in type 1 diabetes (T1D) management, particularly in pediatric populations." (PMID 41010993, 2025). "A case series of fulminant type 1 diabetes with residual insulin secretion will be needed for further verification." (PMID 40406776, 2025). "Using an experimentally induced type 1 diabetic animal model, we have investigated for many years the diabetic damages of enteric neurons and intestinal milieu and the effects of exogenous insulin replacement in their prevention." (PMID 40497986, 2025). "Hybrid closed-loop insulin delivery systems have become the standard of clinical care to manage type 1 diabetes." (PMID 39146468, 2025). "T1DM, also known as insulin-dependent diabetes, occurs due to the autoimmune destruction of the insulin-producing β-cells in the pancreas, leading to an absolute insulin deficiency." (PMID 39791180, 2025). "Type 1 diabetes (T1D) is a chronic disease characterized by insufficient insulin production, typically occurring during childhood or adolescence." (PMID 40556970, 2025). "In the case of teplizumab, the treatment had been given to individuals newly diagnosed with (stage 3) type 1 diabetes in five previous trials with the aim of preserving endogenous insulin production and providing data on safety." (PMID 40768045, 2025). "Although mFicDR371S/R371S mice appear healthy overall, they exhibit signs of insulin-dependent diabetes, characterized by glucose intolerance and impaired insulin secretion." (PMID 40073934, 2025). "Type 1 diabetes is a life-threatening, chronic disease resulting from T cell-mediated autoimmunity against insulin-producing beta cells in the pancreas." (PMID 39670998, 2025). "Type 1 diabetes primarily affects children and young adults, requiring continuous insulin therapy for survival." (PMID 40006246, 2025). "Nonetheless, ongoing development of ultra‐rapid insulin analogues and refinement of closed‐loop algorithms are warranted to further optimise glycaemic outcomes and reduce user burden in type 1 diabetes." (PMID 40815068, 2025).
type 1 diabetes (continued). "Since the discovery of insulin >100 years ago, patients with type 1 diabetes have been waiting for a landscape change in their management." (PMID 40852189, 2025). "Misdiagnosing type 1 diabetes as type 2 diabetes often leads to delayed insulin treatment, which can lead to severe complications." (PMID 40569436, 2025). "This system has demonstrated superior time‐in‐range, reduced HbA1c, and improved glycemic outcomes compared to standard insulin therapy in type 1 diabetes." (PMID 41214779, 2025). "Type 1 diabetes mellitus (T1DM) is characterized by a severe autoimmune attackagainst beta-cells by macrophages and T cells, resulting in the chronichyperglycemia, and a lifelong dependence on insulin." (PMID 40261241, 2025). "Comparison of patient satisfaction between different lines of insulin treatment among patients with type 1 diabetes." (PMID 41250728, 2025). "Patients with type 1 diabetes and special-type diabetes generally had a younger age of onset, longer disease duration, and extended insulin usage, resulting in higher EIAS incidence rates." (PMID 41585798, 2025). "Type I diabetes (T1D) is a chronic autoimmune disease characterized by the destruction of insulin-producing cells in the pancreas, leading to insufficient insulin production and the inability to regulate blood glucose levels properly." (PMID 40852183, 2025). "Type 1 diabetes (T1D) is an autoimmune condition characterized by the destruction of insulin-producing pancreatic beta cells, leading to lifelong insulin dependence and significant complications." (PMID 40362176, 2025). "Type 1 diabetes (T1D) is a complex chronic illness that needs a holistic approach based on insulin use, dietary modifications, and exercise." (PMID 40886244, 2025). "Youth living with type 1 diabetes (T1D) are increasingly choosing automated insulin delivery (AID) systems to manage their blood glucose." (PMID 40920375, 2025). "Fatty acid profile of the skeletal muscle phospholipid fraction of Wistar rats induced to develop type 1 diabetes by alloxan and the influence of insulin and Arasco oil (rich source of AA) on the same." (PMID 40005295, 2025). "The data showed that approximately 78% of patients were taking drugs belonging to the class of biguanides, 7% GLP-1 agonists, and the remaining 15% were in pharmacological therapy with insulin, alone or in combination, for the treatment of type 1 diabetes." (PMID 41148760, 2025). "While typical fulminant type 1 diabetes shows irreversible insulin depletion after onset, in this case, insulin secretion was restored." (PMID 40406776, 2025). "In contrast, our study of the effects of an LC diet over six months offers insights into how sustained carbohydrate reduction and insulin adjustments impact bone metabolism in adolescents with type 1 diabetes." (PMID 41470880, 2025). "AI is often embedded in type I diabetes mHealth apps to enable advanced features, such as glucose level forecasting and insulin dose adjustments." (PMID 40801339, 2025). "We draw data from the OhioT1DM dataset, which contains CGM readings at 5-min intervals, insulin delivery records, meal carbohydrate logs, and heart-rate measurements for Type-1 diabetic patients over 8-week observation windows." (PMID 41374669, 2025). "From several previous studies we know the CV preventive effects of intensive insulin treatment and striving for normoglycemia in type 1 diabetes." (PMID 40034566, 2025). "Clinical trials have demonstrated the benefits of insulin pump therapy compared with multiple daily injections (MDI) in type 1 diabetes." (PMID 40390300, 2025). "Prof. Salti was also among the researchers who noted that type 1 diabetes patients receiving intensive insulin therapy had higher leptin levels compared to those receiving conventional insulin therapy." (PMID 40918806, 2025).
type 1 diabetes (continued). "The presented case describes the forensic and subsequent legal aspects of a fatal case of combined methamphetamine and insulin intoxication leading to death in a woman with Type I diabetes." (PMID 38965163, 2025). "In both patients and animal models, inducing similar levels of hypoglycemia e.g., through insulin overdose, can lead to functional brain failure and death, as seen in type 1 diabetes." (PMID 40702267, 2025). "Once‐daily insulin provides superior HbA1c reduction compared to once‐weekly insulin in type 1 diabetes, while fasting blood glucose levels remain comparable." (PMID 40186384, 2025). "Type 1 diabetes occurs when the immune system damages cells in the pancreas that make and release insulin, a hormone needed to control sugar (glucose) levels in the blood." (PMID 40520684, 2025). "The patient was diagnosed with type 1 diabetes and initiated long-term insulin therapy, including aspart and detemir insulin." (PMID 41585813, 2025). "Type 1 diabetes is an autoimmune disorder characterized by the destruction of insulin-producing β cells in the pancreas, leading to absolute insulin deficiency." (PMID 40407447, 2025). "In the Canadian Closed-Loop Insulin in Mothers with Type 1 Diabetes and Baby feeding practices (CLIMB) study, HCL therapy was started denovo one week after birth." (PMID 39884300, 2025). "The administration of exogenous insulin is lifesaving for type I diabetes but still entails several injections per day since its pharmacokinetics differ from those of endogenous two-phase insulin secretion into portal circulation." (PMID 41155898, 2025). "Previous studies evaluating the efficacy of URIL with AID systems in type 1 diabetes employed a hybrid closed‐loop approach or compared fully closed‐loop insulin delivery with standard (non‐AID) insulin pump therapy." (PMID 40815068, 2025). "Automated insulin delivery systems (AIDs) allow youths with type 1 diabetes (T1D) to achieve optimal glucose control." (PMID 39126517, 2025). "Fatty acid profile of the liver phospholipid fraction of Wistar rats induced to develop type 1 diabetes by alloxan and the influence of insulin and Arasco oil (rich source of AA) on the same." (PMID 40005295, 2025). "Physicochemical properties, biosafety (cytotoxicity, skin barrier recovery, boron leaching), and in vivo efficacy in a type 1 diabetic mouse model were evaluated in comparison to a subcutaneous (SC) insulin injection." (PMID 41471093, 2025). "It is suggested that fulminant type 1 diabetes presents with a variety of clinical conditions including insulin secretory capacity." (PMID 40406776, 2025). "The FDA-approved UVA/Padova simulator, a widely recognized tool for modeling glucose-insulin dynamics in patients with type 1 diabetes, was used to generate realistic, diverse patient data." (PMID 40614090, 2025). "Preservation of endogenous insulin production is viewed as one of the focus areas in the development of new treatment options for people with type 1 diabetes." (PMID 41224288, 2025). "Diabetic ketoacidosis remains a severe complication in type 1 diabetes, arising from insufficient insulin levels and accelerated lipolytic rate, leading to increased β-oxidation of NEFA and ketone body production in the liver." (PMID 40210728, 2025). "Type 1 diabetes (T1D) is a polygenic autoimmune disease characterized by destruction of insulin-producing pancreatic β-cells." (PMID 41303901, 2025). "Type 1 diabetes (T1D) is an autoimmune disease characterized by the progressive destruction of insulin-producing pancreatic beta cells, resulting in severe metabolic consequences and a lifelong dependence on exogenous insulin administration." (PMID 41289263, 2025). "In insulin treatment for type 1 diabetes, intermittent scanning continuous glucose monitoring (isCGM: FreeStyle® Libre), in which a sensor is adhered to the skin, is often used to monitor blood glucose fluctuations and manage glucose levels." (PMID 40382628, 2025).